INS (insulin)
Diseases named in the same sentence as INS in open-access papers (continued):
Sharing a sentence is not in itself a finding about the gene and the disease.
Insulin resistance (continued). "It has been recently suggested that selective impairment of insulin signaling cascades in insulin resistance also occurs in the kidney." (PMID 27247938, 2016). "Remarkably, chronic oxidative stress increased IRS-1(ser307) phosphorylation and insulin resistance whereas acute oxidative stress rescued insulin sensitivity and insulin signaling through redistribution of active cytoplasmic JNK into the nucleus." (PMID 27695421, 2016). "The present study found that two Wnt proteins, WNT3a and WNT4, are specifically secreted by skeletal muscle and WAT during the development of insulin resistance and play an important role in crosstalk between insulin-resistant tissues and pancreatic β-cells." (PMID 27527335, 2016). "Resistin has been associated with insulin resistance and pro-inflammatory properties, along with impaired insulin secretion, and is believed to be an important link between obesity, insulin resistance and T2D." (PMID 27536890, 2016). "Anti-inflammatory cytokines help in maintaining insulin sensitivity in the lean adipose tissue, while accumulation of pro-inflammatory cytokines in obesity leads to insulin resistance." (PMID 27148161, 2016). "In contrast with the severe insulin resistance in P467L PPARγ patients, the P465L PPARγ mutant mice have normal insulin sensitivity." (PMID 27483259, 2016). "Exact analysis of equine insulin in blood samples is the key element for assessing insulin resistance or insulin dysregulation in horses." (PMID 27613127, 2016). "Their health, however, progressively worsens with age, with two-week-old sir2 mutants displaying lipid accumulation, fasting hyperglycemia, and reduced insulin signaling accompanied by insulin resistance." (PMID 27058248, 2016). "The results of the insulin tolerance tests suggest that ND-fed Aox4−/− animals show a mild and short-lived increase in insulin resistance relative to WT mice, which translates into higher AUC values." (PMID 27456060, 2016). "ITT performed at 6 months revealed that the decrease in blood glucose after insulin injection was significantly impaired in SL mice, showing insulin resistance in this group." (PMID 27465434, 2016). "They found that CB stimulation by insulin seems to be involved in the development of insulin resistance and hypertension." (PMID 26920146, 2016). "GlycA was associated with measures of insulin resistance including fasting insulin (r = 0.37, P <0.02), homeostasis model assessment (HOMA; r = 0.39, P <0.02), and insulin sensitivity (r = −0.34, P <0.04)." (PMID 27067270, 2016). "In the patients with NAFLD or HFD-induced animals, the circulating fasting insulin is commonly elevated due to the insulin resistance." (PMID 27104558, 2016). "An SL diet aggravated β cell function and adipose tissue inflammation in lean βGck+/− mice with impaired insulin secretion in response to glucose and normal insulin resistance, compared with an SO diet." (PMID 26937254, 2016). "A close relationship between the inflammatory response and insulin resistance has been proposed on the basis of the suppression of insulin-dependent glucose uptake in sepsis patients." (PMID 27148161, 2016). "Insulin resistance induced by a high fat diet involves decreased protein levels of insulin signaling pathway factors, such as insulin receptor (IR), phosphoinositide 3-kinase (PI3K), and Akt4,5." (PMID 27508151, 2016). "These high levels of oxidative stress were associated with a significant increase in glucose intolerance and increased plasma insulin concentrations, both indicative of metabolic dysfunction consistent with insulin resistance." (PMID 27438860, 2016). "Although WD SW-fed mice remained initially insulin sensitive at 8 weeks, they developed significant insulin resistance at 16 weeks which was sustained up to 52 weeks." (PMID 27261415, 2016). "OGTT indicates the relative roles of insulin secretion and insulin resistance in the progression of glucose intolerance." (PMID 27216600, 2016).
Insulin resistance (continued). "On the one hand, hepatic steatosis and impairment reduces insulin clearance and, over time, greater insulin resistance." (PMID 27314342, 2016). "On the other hand, it was also demonstrated that lactate induced insulin resistance, and lactate treatment inhibited insulin action by inhibiting the insulin receptor substrate-1 (IRS-1) and IRS-2 mediated PI3K and PKB pathways." (PMID 26938239, 2016). "This regulation of energy metabolism takes place in multiple peripheral tissues including skeletal muscle, liver, adipose tissues, and pancreatic beta cells which all function in either insulin sensitivity or insulin resistance." (PMID 26990883, 2016). "Increasing insulin sensitivity (i.e., improving insulin resistance and glucose tolerance) is important in preventing or improving T2DM." (PMID 27916833, 2016). "CH and RH displayed increased glucose intolerance, insulin resistance and glucose-stimulated insulin secretion." (PMID 27633083, 2016). "Insulin resistance in obesity and type 2 diabetes is characterized by fewer insulin stimulated glucose transport and less metabolism in skeletal muscle and adipocytes." (PMID 27070590, 2016). "The intraperitoneal glucose tolerance test and intraperitoneal insulin tolerance test demonstrated that HFD-induced insulin resistance in NTG mice was further exacerbated by TRAF3 overexpression in the liver." (PMID 26882989, 2016). "An novel finding of the present study on possible pathways for insulin resistance is that elevated circulating irisin levels improve insulin resistance indirectly through decreasing fasting insulin." (PMID 27473122, 2016). "It's important that MBBP can reduce insulin resistance, which results in a decrease of the serum insulin level." (PMID 27257845, 2016). "Insulin resistance is defined as a pathological condition in which a cell, tissue or organism requires above-normal quantities of insulin to respond normally." (PMID 27423183, 2016). "Patient 1 had a significant reduction in blood insulin level and a decrease in homeostatic model assessment-insulin resistance." (PMID 26757831, 2016). "An insulin resistance test showed that plasma glucose concentrations at 30 min after insulin injection were higher in the TAC group than in the sham group." (PMID 27659110, 2016). "Improved glucose homeostasis was observed as reflected by decreased levels of FPG and serum insulin as well as decreased HOMA-IR values (homeostasis model of assessment of insulin resistance)." (PMID 27983572, 2016). "T2DM is characterised by insulin resistance, declining insulin production and eventual pancreatic β cell failure." (PMID 27795741, 2016). "Various well established non-steroidal anti-inflammatory drugs (NSAIDs) and cyclooxygenase inhibitors (e.g., ibuprofen, naproxen) are able to improve glucose-mediated insulin release, glucose tolerance, and reduce the insulin resistance in diabetic patients." (PMID 27527213, 2016). "Our data demonstrated that compared with obese patients, FGF21 levels were positively correlated with obesity-related AN and markers of insulin resistance (fasting insulin, HOMA-IR)." (PMID 27190511, 2016). "Based on our early work and that of others, this is likely to result in a decrease in muscle insulin sensitivity and contribute substantially to pregnancy-induced insulin resistance." (PMID 27559358, 2016). "Diabetes mellitus is a multifactorial disease characterized by a high value of plasma glucose due to either pancreatic failure to secrete insulin (type 1) or cellular insulin resistance (type 2)." (PMID 28933391, 2016). "Physical activity has been shown to significantly improve insulin sensitivity,presenting as an effective treatment strategy for insulin resistance." (PMID 27143172, 2016). "It is very probable that Lf plays a positive role in improving insulin sensitivity considering its impact on OxS and inflammation, two pathophysiological processes leading to adverse metabolic conditions such as insulin resistance." (PMID 27902700, 2016).
Insulin resistance (continued). "Pancreatic β cells need to dramatically increase their insulin production to fit the demand under chronic insulin resistance and, hence, pancreatic islets from mice and humans with T2D show signs of ER UPR." (PMID 27148273, 2016). "As reported in previous study, there is insulin resistance in patients with T2DM, in other words, pancreas islet secretes more insulin and C peptide, which causes hyperinsulinemia." (PMID 27419144, 2016). "Data were collected on waist circumference (WC), body mass index (BMI), waist-to-hip ratio (WHR), body fat (BF%), fasting blood glucose, plasma lipids, adiponectin, leptin, insulin and homeostasis model for assessment of insulin resistance (HOMA-IR)." (PMID 27189377, 2016). "CKO mice on HFD presented significantly increased markers of insulin resistance, such as fed and fasting plasma insulin and HOMA-IR." (PMID 27597806, 2016). "It has been reported that chronic nicotine administration can reduce insulin resistance in obese mice and enhance insulin sensitivity in normal rats via α7nAChR." (PMID 27065867, 2016). "Those adipocyte effects that can be measured as the product of fasting plasma free fatty acids by insulin concentration have been called adipose tissue insulin resistance (Adipo-IR)." (PMID 28127113, 2016). "Insulin action is to reuptake and store glucose as glycogen, while insulin resistance finally results in T2DM." (PMID 27147943, 2016). "Accumulating evidence suggests that lipid-induced insulin resistance is at least partially mediated by diacylglycerols that activate novel protein kinase C isoforms with subsequent inhibition of insulin action in liver and skeletal muscle." (PMID 27736893, 2016). "Dysfunctional insulin sensitivity, or insulin resistance, is dependent on ectopic fat accumulation in liver, visceral adipose tissue, and skeletal muscle." (PMID 27938404, 2016). "Epidemiologic data suggest that insulin resistance with hyperinsulinaemia, as well as increased insulin and insulin-like growth factor-1 (IGF-1) signalling account for the relationship between these conditions." (PMID 27795741, 2016). "Low 25OHD levels were also associated with higher thigh IMAT, and thigh IMAT was associated with higher triglycerides and insulin, and lower HDL cholesterol and higher insulin resistance." (PMID 27916865, 2016). "SD group as well as UP and FU had a similar insulin response in the first 90 min of the experiment, while HF group showed a behavior that characterizes insulin resistance." (PMID 27527189, 2016). "Impaired lipid metabolism is related to the development of insulin resistance, so the regulation of lipid metabolism by insulin must be assessed." (PMID 26934990, 2016). "Given the range of effects of insulin in the brain, including neurogenesis, neurite outgrowth, and modulation of catecholamine release/uptake, other possible links between insulin resistance and dementia need to be considered." (PMID 27303627, 2016). "Therapies which improve insulin signaling and prevent the development of insulin resistance remain important strategies for reducing hepatic lipotoxicity and associated diseases such as NAFLD." (PMID 27128935, 2016). "A high insulin concentration most likely results from insulin hypersecretion in order to compensate for peripheral insulin resistance." (PMID 27136422, 2016). "Individuals with diminished beta cell reserve are less able to cope with increased demand for insulin imposed by the development of insulin resistance, and develop hyperglycemia consequent to beta cell exhaustion." (PMID 28702252, 2016). "In response to HFD-induced insulin resistance, Lxrα-Tg mice nevertheless displayed increased myocardial glucose uptake, mediated in part by restoration of insulin-dependent GLUT4 through increased AMPK phosphorylation." (PMID 26684450, 2016). "Increasing insulin resistance precipitates a reduction in glucose uptake by the liver and a compensatory increase in circulating levels of insulin." (PMID 27314342, 2016).
Insulin resistance (continued). "Peripheral insulin resistance is then defined by a decrease in insulin-dependent glucose transport at the level of target tissues due to defects at both the insulin receptor and/or postreceptor signaling." (PMID 27725832, 2016). "In vivo knockdown of March1 expression in liver and WAT enhanced insulin sensitivity in regular chow-fed mice and prevented insulin resistance in high-fat-fed mice." (PMID 27577745, 2016). "In animal experiments, it has been reported that an interaction between excess high fat and BCAAs in development of insulin resistance is mediated by impaired insulin signaling in the liver and the muscles." (PMID 27338465, 2016). "The strong inhibition of DPP4 protease activity by hypoxia and the insulin-mediated increase in DPP4 indicate that DPP4 represents an important marker for early detection of insulin resistance." (PMID 26881257, 2016). "DM2 and obesity are diseases linked to low grade chronic inflammatory activity, resulting in impaired insulin sensibility and insulin resistance." (PMID 28076480, 2016). "All diets induced a similar increase in body weight and insulin resistance, indicating that the observed brain changes were independent from body weight gain and peripheral insulin sensitivity." (PMID 27583555, 2016). "The pharmacological therapy will be used while combined with some lifestyle changes and its aim is to decrease insulin resistance, increase insulin secretion, slow down the absorption of glucose fed state." (PMID 27974926, 2016). "Given the many syndromes associated with insulin resistance, including T2DM and coronary heart diseases, an elevated TG/HDL-C ratio supports more aggressive efforts to enhance insulin sensitivity." (PMID 27115999, 2016). "In the present study, GEB potentiated hypothalamic insulin signaling (pAkt → pGSK-1β) in parallel with improving hepatic insulin resistance in partial Px rats." (PMID 26978400, 2016). "A more sensitive method for assessing insulin sensitivity, like the euglycemic-hyperinsulinemic clamp, will probably be needed in order to study the degree of insulin resistance in more detail." (PMID 26751381, 2016). "hsCRPpositively correlated with fasting glucose(r=0.816), fasting insulin (r=0.518), insulin resistance(r=0.609), LH/FSH ratio (r=0.631) andprolactin (r=0.688, P<0.01), and had a negativecorrelation with FSH (r=-0.514, P<0.001)." (PMID 27123196, 2016). "Surveillance for fasting insulin and indirectly insulin resistance is thus beneficial, particularly among an apparently healthy overweight and obese paediatric population, in order to halt cardio-metabolic risk factors as they mature into adulthood." (PMID 27824069, 2016). "These pro- and anti-inflammatory cytokines can enhance insulin resistance directly in adipocytes, muscle, and hepatic cells, leading to systemic disruption of insulin sensitivity and impaired glucose homeostasis." (PMID 27478850, 2016). "How do these metabolites involve in the regulation of insulin signaling and by what mechanism do they mediate insulin resistance?" (PMID 26899878, 2016). "Genetic deletion of NR4A1 increases susceptibility to diet-induced obesity and insulin resistance, and loss of NR4A1 expression in skeletal muscle impairs insulin signaling, markedly reduces GLUT4 protein expression, and increases triglyceride content." (PMID 27322146, 2016). "Overall between 50 and 70% of women with PCOS had demonstrable insulin-resistance, which results in a compensatory increase in insulin secretion by β-islet cells of the pancreas." (PMID 27579037, 2016). "Since there is a relationship between PCOS and insulin resistance, administration of drugs to ameliorate insulin sensitivity and ovarian activity is suggested to treat this syndrome." (PMID 28331909, 2016).
Insulin resistance (continued). "Type 2 diabetes (T2D) represents a broad spectrum of disorders, ranging from severe insulin resistance with only minimal insulin secretory defect to profound insulin secretory defect with minimal insulin resistance." (PMID 28702252, 2016). "Dietary intervention capable of lowering the insulin demand, improving insulin sensitivity, or both, is likely to reduce the incidence of disorders related to insulin resistance, as indicated by interventional studies." (PMID 27664051, 2016). "Insulin resistance and impaired insulin secretion lead to type 2 diabetes, which has the features of chronic metabolic disorder and high levels of blood glucose." (PMID 27754463, 2016). "The genotype AA of the rs4730153 SNP was significantly associated with fasting glucose, fasting insulin and HOMA-IR (Homeostasis model assessment-insulin resistance) after adjustment for gender, age, BMI and waist circumference." (PMID 27166797, 2016). "Metabolic syndrome is believed to decrease insulin effects due to insulin resistance, thus influencing the function to suppress plasma free fatty acids." (PMID 27802330, 2016). "The insulin resistance index: (AUCs of insulin) × (AUCs of glucose) was also greater in diabetic CAD group than non-diabetic CAD group (11,943 ± 8730 vs 6938 ± 4587, P = 0.0228)." (PMID 26439243, 2016). "Tumor necrosis factor-α (TNF-α) is overproduced in the adipose tissue of obese animals and humans and contributes to the insulin resistance by targeting several components of the insulin signaling pathway." (PMID 28042862, 2016). "Clinical studies found increased insulin resistance and decreased insulin concentrations in the cerebrospinal fluid of patients with neurodegenerative disorders." (PMID 27065205, 2016). "This technique allows monitoring of cell type specific insulin sensitivity/resistance in real-time in the context of whole body insulin resistance during progression and intervention of disease." (PMID 26899548, 2016). "This technique combined with overall insulin tolerance tests allows to monitor the dynamics of β-cell insulin resistance in the context of overall insulin resistance in the development and progression of T2DM." (PMID 26899548, 2016). "In summary, HUA inhibited insulin signaling and induced insulin resistance in cardiomyocytes in vivo and cardiac tissue in vitro." (PMID 26836389, 2016). "Pro-inflammatory adipokines obstruct the insulin-signaling pathway in peripheral tissues and promote the development of insulin resistance." (PMID 26999199, 2016). "The homeostasis model assessment for insulin resistance (HOMA-IR) was used to determine insulin resistance based on the fasted insulin and glucose levels after 30 weeks on the diet." (PMID 27402965, 2016). "Our mouse model showed impaired glucose tolerance and insulin tolerance at 15 and 30 min after glucose or insulin injection with insulin resistance." (PMID 26836389, 2016). "Genetic deletion of the eNOS or nNOS genes in mice triggers vascular impairment and insulin resistance likely due to impairment of insulin-stimulated glucose uptake by skeletal muscle and other insulin sensitive tissues." (PMID 26770984, 2016). "Thiazolidinediones (TZD) are a class of insulin sensitizing drugs which are selective ligands of PPARγ and target insulin resistance." (PMID 27128935, 2016). "An investigation was conducted on the potential predictors of fasting insulin and insulin resistance among overweight/obese adolescents in a developing Asian country." (PMID 27824069, 2016). "IFG has been related to raised hepatic glucose output and dysfunction in insulin secretion, whereas IGT is associated with peripheral insulin resistance." (PMID 27491662, 2016). "Several earlier studies have shown that Akt phosphorylation is impaired in insulin-resistant tissue; this is in contrast to other reports stating that Akt phosphorylation is unaffected by insulin resistance." (PMID 27738449, 2016).